METTL1 (methyltransferase 1, tRNA methylguanosine)
Diseases named in the same sentence as METTL1 in open-access papers (continued):
Sharing a sentence is not in itself a finding about the gene and the disease.
tumor (continued). "The expression level of METTL1 exhibits a threshold effect on cell fate; high expression influences tumor prognosis by promoting apoptosis or inhibiting autophagy." (PMID 40809384, 2025). "Tumor microenvironmental conditions, including hypoxia, also influence METTL1 expression, often promoting its upregulation." (PMID 41562049, 2025). "Clinical data analysis revealed that high METTL1 expression correlates significantly with larger tumor size, elevated serum AFP levels, tumor vascular invasion, and reduced survival rates." (PMID 40809384, 2025). "The effect of m7G on ICC is mainly reflected by the tumor promoting function of METTL1 and WDR4, mainly affecting cell cycle arrest and translation damage, with cell cycle arrest occurring after translation damage." (PMID 39850560, 2024). "In fact, several studies highlight METTL1’s regulatory role of the immune landscape in several tumor types towards a more anti-tumoral profile." (PMID 38476632, 2024). "For example, METTL1 is associated with advanced tumor stage, vascular invasion, and poor prognosis in HCC patients, and promotes tumor progression by increasing the translation of target mRNA by promoting m7G modification of tRNA." (PMID 38351139, 2024). "Our study uncovered the crucial tumor-suppressive role of METTL1-mediated tRNA m7G modification in BC by promoting the translation of GADD45A and RB1 mRNAs, selectively blocking the G2/M phase of the cell cycle." (PMID 38822363, 2024). "The immunohistochemical staining results of the mice tumor tissue further validated observed expression alterations of METTL1, which were consistent with the findings from the in vitro cell experiments." (PMID 38693422, 2024). "Upregulation of METTL1 and WDR4 was associated with advanced tumor stage, vascular invasion status, and poor patient survival." (PMID 39850560, 2024). "Conversely, the oe-METTL1 mice group exhibited higher signal intensity on the fluorescence images, indicating an increase in tumor growth activity compared to the oe-NC group." (PMID 38693422, 2024). "Consistent with the prevalence of METTL1 amplification, METTL1 was significantly upregulated in GBM tumours." (PMID 39041608, 2024). "We also revealed that the METTL1/WDR4 complex promoted cell proliferation, inhibited cell apoptosis in AML cells, suggesting that METTL1 acts as a tumor accelerator in AML." (PMID 38268051, 2024). "More recently, work in our group has unveiled an alternative mechanism through which METTL1 regulates tumor progression in PCa." (PMID 38476632, 2024). "In conclusion, studies on mouse models have shown that silencing METTL1 can inhibit tumor occurrence and development, increase mouse survival, and enhance the efficacy of immunotherapy targeting CTLA4 and PD1." (PMID 38693422, 2024). "To further elucidate the role of METTL1 in vivo, we established xenograft tumor models using MCF-7 cells." (PMID 38822363, 2024). "The results revealed that the sh-METTL1 mice group displayed lower signal intensity on the fluorescence images, indicating a decrease in tumor growth activity compared to the sh-NC group." (PMID 38693422, 2024). "In prostate tumours, METTL1 is also overexpressed both in primary and advanced stages, suppressing immune effectors, interferon pathways, and tumour growth suppression." (PMID 38943267, 2024). "Taken together, the in vivo results prove that METTL1 has the potential to potentiate the sensitivity to abemaciclib, thereby inhibiting BC tumor growth." (PMID 38822363, 2024). "METTL1 stands as the most extensively studied m7G methyltransferase within the context of tumor immunity." (PMID 38385078, 2024). "Immunohistochemistry staining was further used to validate the expression of METTL1 by tissue micro-array analysis for a large cohort with 93 tumor tissues and 87 non-tumor tissues." (PMID 37692515, 2024).
tumor (continued). "Recent studies have indicated that chemotherapeutic treatments in diverse tumor cells can induce mRNA m7G modification mediated by METTL1 and QKI7." (PMID 38385078, 2024). "Our data demonstrated that METTL1 overexpression significantly suppressed tumor growth compared to the control group." (PMID 38822363, 2024). "Taken together, these observations offer compelling evidence supporting the tumor-suppressor function of METTL1 in BC tumorigenesis." (PMID 38822363, 2024). "The METTL1-dependent m7G status significantly influences tumor proliferation, therapy response, metastasis and the immune microenvironment." (PMID 38476632, 2024). "In HCC, upregulation of METTL1 and WDR4 is associated with advanced tumor stage, vascular invasion status, and poor patient survival." (PMID 39850560, 2024). "METTL1 plays an influential part in the progression of various tumors, impacting tumor cell proliferation, autophagy, and sensitivity to radiotherapy and chemotherapy." (PMID 38822363, 2024). "In conclusion, our study underscores the critical role of METTL1 in PCa and the tumour microenvironment." (PMID 37516825, 2023). "WDR4 forms a methyltransferase complex with Methyl transferase-like protein 1 (METTL1), promoting the translation of tumor-related mRNA by influencing m7G modification of tRNA." (PMID 37783676, 2023). "In this study, a co-expression network of METTL1 / WDR4 was constructed by Pearson correlation coefficient based on TCGA-HCC cohort (tumor: n = 370) using R software "WGCNA "package." (PMID 37528384, 2023). "Further observations revealed that METTL1-knockout mice had a lower tumor burden and a longer survival than wild-type controls." (PMID 37679400, 2023). "The methyltransferase complex formed by WDR4 and METTL1 promotes the translation of the target mRNAs and promotes tumor progression." (PMID 37783676, 2023). "At the same time, the knockdown group (CTPB + shMETTL1) was faster growing and had larger tumor volume and mass compared to the knockdown METTL1 group." (PMID 37599359, 2023). "In human colon and lung cancer cells, METTL1 was required for m7G modification of the tumor suppressor microRNA let-7e to maintain high levels of mature let-7e, whose downregulation leads to high mobility group AT-hook 2 (HMGA2) overexpression." (PMID 37612540, 2023). "Docetaxel-treated METTL1-KO tumour cells exhibited dysregulated autophagy, increased DNA damage and apoptosis, leading to a reduction in cells re-entering the cell cycle (Ki67+cells) compared to wild-type cells." (PMID 37660182, 2023). "In adrenocortical carcinoma, immunofluorescence revealed that high expression of METTL1 in tumor cells was inversely proportional to CD8 + T and directly proportional to the infiltration rate of macrophages." (PMID 37710294, 2023). "The results of our research provide compelling evidence highlighting the pivotal role of METTL1 in regulating the immune response against tumours." (PMID 37516825, 2023). "The depletion or overexpression of METTL1 significantly affected the viability, proliferation, migration, and metastasis of various tumor cell types." (PMID 37275549, 2023). "To elucidate the impact of Mettl1 inhibition on the reprogramming of the immune tumour composition, we employed an analysis of immunomodulatory molecules, including cytokines and chemokines, as surrogate markers of the immune cells present in the tumour." (PMID 37516825, 2023). "Our findings indicate that inhibiting METTL1 activity leads to favourable changes within the tumour, such as an increased presence of anti-tumoural cytokines and the infiltration of cytotoxic immune cells, including M1-like macrophages and CD8+ T cells." (PMID 37516825, 2023). "While Docetaxel treatment induced a modest growth reduction in wild-type tumours, it significantly reversed the growth and reduced the size of METTL1-KO tumours, almost to the initial stages of tumour formation." (PMID 37660182, 2023).
tumor (continued). "In summary, our data indicate that METTL1 expression inversely correlates with activation of the IFN pathway in PCa cells and tumours, and METTL1 inhibition translationally activates the IFN signalling pathway." (PMID 37516825, 2023). "This indicates that the immunoregulatory effect of METTL1 is greater than that of WDR4 in the tumor microenvironment." (PMID 36635678, 2023). "The METTL1 / WDR4 complex currently promotes tumor development by mediating tRNA m7G methylation modification." (PMID 37528384, 2023). "METTL1 expression consistently increased from primary to metastatic human tumours, and high expression of METTL1 showed worse prognosis in Cambridge, Stockholm, and Taylor cohorts." (PMID 37516825, 2023). "Using the ROC plotter platform, we analysed the expression levels of METTL1 in several tumour types treated with anti-PD1 therapy." (PMID 37516825, 2023). "Inhibiting METTL1 expression in tumours impedes their progression and reverts them to a state resembling healthy tissue." (PMID 37660182, 2023). "Because tumour cell tRNAs have been shown to be methylated by METTL1, we postulate a potential connection between the loss of m7G deposition and stress signalling." (PMID 37660182, 2023). "Our study contributes to this understanding by demonstrating that inhibiting METTL1 leads to enhanced infiltration of cytotoxic macrophages and cytotoxic T cells into tumours, indicating that METTL1 serves as a key mediator of intratumoural immune responses." (PMID 37516825, 2023). "More than half of the m7G-related genes were significantly upregulated in tumor samples, such as METTL1, WDR4, EIF4E, LARP1, and LSM1." (PMID 36761423, 2022). "It was shown that the suppression of METTL1 or WDR4 in tumor cell lines in in vitro experiments leads to the arrest of cell proliferation, increased apoptosis, reduced colony formation and migration, and reduced tumor formation in in vivo experiments." (PMID 36012529, 2022). "METTL1, a m7G methyltransferase, is upregulated in tumor-bearing patients compared to healthy controls." (PMID 36118897, 2022). "METTL1 regulates cell proliferation, with potentially oncogenic effects on tRNA but tumor-suppressive activity in miRNA maturation, and is amplified explicitly in HCC and is correlated with poor prognosis." (PMID 36120301, 2022). "For example, METTL1 mediates m7G modification on tRNA, drives oncogene transformation and tumor formation by upregulating the translation of specific mRNAs such as growth-promoting proteins." (PMID 36226166, 2022). "METTL1 is highly upregulated in BC tissues, and its expression is positively correlated with advanced clinical stage and high tumor grade." (PMID 35590385, 2022). "In conclusion, the oncogenic role of miR-760 and tumor suppressor role of ATF3 help to explain the potential regulatory mechanism of METTL1 in BCa." (PMID 36396627, 2022). "Our data showed that knockout of Mettl1 in the tumor-bearing mice significantly decreased the lesion area and numbers of dysplasia and ESCC." (PMID 35304469, 2022). "Another study also suggested a tumor promotor role of METTL1 in LC by demonstrating its ability to accelerate proliferation and autophagy through the AKT/mTORC1 signaling cascade." (PMID 35590385, 2022). "The relationship between METTL1 expression or activity and tumor immune infiltration were analyzed to explore the significance of METTL1 in tumor immunotherapy." (PMID 35432338, 2022). "Our team studied the expressing level of 2 m7G-associated genes METTL1 and WDR4 in 18 tumor types and found that these two m7G-related genes were differentially expressed in many tumors, showing significant heterogeneity." (PMID 35812727, 2022). "After DEN/sorafenib treatment for 18 weeks, massive tumor burden was developed in esophagus of the Mettl1 cKI mice, while only few and small lesions occurred in the esophagus of control mice." (PMID 35304469, 2022).
tumor (continued). "Further analysis showed that tumor cell lines with higher METTL1 expression were more sensitive to drugs targeting chromatin histone methylation, ERK-MAPK and WNT signaling pathways." (PMID 35432338, 2022). "To study the effect of METTL1 on ESCC progression in vivo, we first induced ESCC formation in the Mettl1 cKO and control mice, then the tumor-bearing mice were treated with tamoxifen to induce Mettl1 knockout in the cKO mice." (PMID 35304469, 2022). "Mice injected with METTL1 knockdown cells showed significantly slower tumor growth, reduced tumor sizes and weights compared with those injected with shGFP ESCC cells." (PMID 35304469, 2022). "Recent studies also reported that METTL1 is involved in tumor development by promoting mRNA processing in an m7G-dependent manner." (PMID 35865472, 2022). "It was discovered that METTL1 acts as a tumor suppressor in CC, overexpression of which can effectively attenuate the proliferation, migration, and invasion of CC cells, in addition to promoting apoptosis." (PMID 35590385, 2022). "METTL1 knockout mice have an anti-tumor microenvironment, with higher infiltration of CD4 + memory T cells, CD4 + naïve T cells, and CD8 + naïve T cells, and lower infiltration of Tregs and Th17 cells." (PMID 35590385, 2022). "In the TCGA database, the expression of METTL1 in the primary tumor (n = 408) was significantly elevated compared to normal subjects (n = 19) (P < 0.001)." (PMID 36396627, 2022). "The important role of METTL1 in BC tumor progression and its value in clinicopathology provides potential ideas for the clinical management and treatment of BC." (PMID 35590385, 2022). "IHC staining of subcutaneous tumor tissues showed significantly reduced protein levels of METTL1 and Ki67, indicating that METTL1 knockdown significantly inhibited NBL proliferation in vivo." (PMID 36071474, 2022). "For example, METTL1, an m7G methyltransferase, has been linked to advanced tumor stage, vascular invasion, and poor prognosis in LIHC patients and facilitates tumor progression through increasing m7G tRNA modification and promoting translation of target mRNAs." (PMID 35938009, 2022). "Previous studies have reported the effect of N7-methylguanosine (m7G) regulator methyltransferase like-1 protein (METTL1) in tumor initiation, metastasis, and chemosensitivity." (PMID 35432338, 2022). "We observed a high expression of METTL1 in tumor samples, which is consistent with the conclusions of previous studies." (PMID 36003341, 2022). "In particular, METTL1-dependent m7G was discovered in a subset of tumor-suppressor miRNAs involved in the inhibition of cell migration, including the let-7 family." (PMID 34282776, 2021). "Co‐expression of myr‐AKT1 and N‐RasV12 resulted in obvious liver enlargement and tumour burden within 4 weeks after injection in Mettl1‐KI group, resulting in significantly upregulation of liver weight to body weight ratio." (PMID 34898034, 2021). "Xenograft assays in mice further confirmed that METTL1 depletion suppressed tumour progression in vivo." (PMID 34936728, 2021). "The levels of METTL1 and WDR4 are elevated in HCC and associated with advanced tumour stages and poor patient survival." (PMID 34898034, 2021). "IHC revealed high METTL1 protein expression in tumour samples and low expression in paratumour tissue." (PMID 34936728, 2021). "METTL1‐depleted and empty vector control T24 cells were implanted into immunodeficient mice via subcutaneous inoculation, and tumour size was determined at different time points." (PMID 34936728, 2021). "Mice injected with METTL1‐depleted T24 cells developed tumours of smaller volume and lower tumour weight, which grew significantly slower than their control cell‐derived counterparts." (PMID 34936728, 2021). "Six weeks after transfection, the control mice showed dramatic liver enlargement and tumour burden, while the Mettl1‐cKO group mice had smaller liver size and decreased tumour burden." (PMID 34898034, 2021).
tumor (continued). "The results indicated that the expression of METTL1 significantly increased with tumor grade, having the highest expression in GBM followed by that in LGG and adjacent tissues." (PMID 34838021, 2021). "Taken together, the in vivo data confirmed that METTL1 knockout inhibited tumourigenesis and progression in both the xenograft mouse model and the zebrafish tumour model." (PMID 34936728, 2021). "To further verify the significance of METTL1 in tumourigenesis in vivo, we employed nude mice as xenograft tumour models." (PMID 34936728, 2021). "Taken together, several METTL genes, including METTL1, METTL2A, METTL4, EEF1AKNMT, and METTL24, had relatively higher frequencies of genetic amplification, deletion, or mutation in various tumor types, notably LUAD, BRCA, and GBM." (PMID 34285249, 2021). "METTL1 plays a role in several biological functions, including cell cycle progression, migration, invasion, angiogenesis, chemo‐ and radiotherapy resistance, energy metabolism and tumour immune microenvironment (TIME) suppression." (PMID 39979979, 2025). "METTL1 up‐regulation decreases the antiproliferative and proapoptotic effects of anlotinib while enhancing cell migration and has a markedly inverse correlation with tumour growth inhibition rates." (PMID 39979979, 2025). "Similarly, METTL1 promoted tumor progression by modulating the expression of oncogenic transcripts via the PI3K/AKT/mTOR signaling pathway in HNSCC." (PMID 40809384, 2025). "In vivo studies further revealed that 5-formamidoimidazole-4-carboxamide ribotide treatment effectively suppressed tumor growth, with overexpression of METTL1 or BRCA1 reversing the inhibitory effects of 5-formamidoimidazole-4-carboxamide ribotide on tumor growth." (PMID 41430564, 2025). "Moreover, METTL1 and its associated core genes are positively correlated with immunosuppressive cell populations, including regulatory T cells (Tregs) and follicular helper T cells (Tfh), suggesting that METTL1 may contribute to shaping an immunosuppressive tumor microenvironment." (PMID 41562049, 2025). "Functional assays revealed that downregulation of TSPAN31 could partially reverse the tumor-promoting effects of METTL1 and CCT2 overexpression." (PMID 41562049, 2025). "Moreover, METTL1 shapes the tumor immune microenvironment by modulating immune cell infiltration, promoting immunosuppressive populations, and contributing to immune evasion, which has implications for immunotherapy." (PMID 41562049, 2025). "In addition, single‐cell RNA sequencing revealed that METTL1 knockout in mouse tumour cells alters the immune landscape and cell‐cell interactions between the tumour and stromal compartments." (PMID 39979979, 2025). "Functionally, overexpressing ATF4 reversed the anti-tumor effect of METTL1 knockdown." (PMID 39870616, 2025). "ATF4 overexpression mitigated the impact of METTL1 knockdown on tumor growth and weight." (PMID 39870616, 2025). "With the advent of high-throughput sequencing and refined RNA modification profiling techniques—such as selective immunoprecipitation, LC-MS/MS quantification, and chemical-based site mapping—the significance of METTL1 and m7G modifications in tumor biology has become increasingly evident." (PMID 41562049, 2025). "The involvement of METTL1 in tumor metastasis is increasingly being recognized." (PMID 40809384, 2025). "Mechanistic studies indicate that METTL1-mediated tRNA m7G modifications preferentially enhance the translation of mRNAs enriched in codons decoded by these tRNAs, thereby promoting the expression of tumor-promoting proteins and driving HCC progression." (PMID 41562049, 2025). "Additionally, quantitative immunohistochemical analysis revealed that the expression of EIF3D, EIF1, LARP1, and METTL1 in the tumor group was significantly higher than in adjacent tissues." (PMID 40018039, 2025).